IGFBP7 (insulin like growth factor binding protein 7)
Diseases named in the same sentence as IGFBP7 in open-access papers (continued):
Sharing a sentence is not in itself a finding about the gene and the disease.
demyelinating disease (2 papers, 2021 to 2023). A broad group of disorders that affect the myelin sheaths that cover the neurons. "In the current investigation, two demyelinating diseases were found to have significantly elevated levels of serum and CSF IGFBP7." (PMID 37174963, 2023). "Prior investigations linked IGFBP7 and LAMP2 to demyelinating disease or MS, while the underlying mechanism remained unknown." (PMID 37174963, 2023). "In these top 10 proteins, IGF2, IGBP7 and SST were the proteins with large fold changes (FC=4.43, 2.60 and 0.17).Besides, we found that IGF2, IGFBP7 and SST are related to demyelinating disease in previous research." (PMID 34489947, 2021).
diffuse gastric adenocarcinoma (2 papers, 2021). An adenocarcinoma arising from the stomach. "As we can see, the mRNA expression of IGFBP7 was significantly upregulated in gastric diffuse adenocarcinoma, intestinal type adenocarcinoma, and mixed adenocarcinoma compared to normal gastric tissues." (PMID 33531979, 2021).
endometriosis (2 papers, 2008 to 2024). The growth of functional endometrial tissue in anatomic sites outside the uterine body. "Analysis of serum IGFBP7 levels in patients with endometriosis revealed that these patients had significantly higher average levels of IGFBP7 than control subjects." (PMID 19019211, 2008). "It is possible that the increased serum IGFBP7 levels seen in patients with endometriosis reflect inflammation in the pelvic cavity and the production of various cytokines, which can elevate IGFBP7 production." (PMID 19019211, 2008). "We found that women with endometriosis had significantly higher serum IGFBP7 levels than normal women." (PMID 19019211, 2008). "IGFBP7 is associated with the pathophysiology of endometriosis, as serum IGFBP7 concentrations in patients with endometriosis are significantly higher than those in the control group, and metformin can upregulate the expression of IGFBP7 in both human and mouse models of endometriosis." (PMID 39081862, 2024).
gastritis (2 papers, 2023 to 2025). Inflammation of the stomach. "In the context of CAG, IGFBP7 may affect the development and progression of gastritis by regulating these processes." (PMID 40012220, 2025).
gestational diabetes (2 papers, 2022 to 2025). Carbohydrate intolerance first diagnosed during pregnancy. "Based on the study of IGFBP1-7 in obese pregnant women, women with gestational diabetes, and their fetuses, Lappas found that preexisting maternal obesity and gestational diabetes are associated with lower levels of IGFBP-1 and IGFBP-7 in maternal and cord plasma." (PMID 35813634, 2022).
hyperplastic polyp (2 papers, 2018 to 2021). A polyp found mainly in the stomach and colon. "However, hypermethylation of p16 and IGFBP7 promoters leads to the surpassing of this senescence barrier, driving the progression of hyperplastic polyps to sessile serrated adenoma/polyps (SSA/P)." (PMID 33672345, 2021). "For example, in early stages of the serrated pathway, mutation of BRAF elevates the expression of tumor suppressor genes p16 and insulin-like growth factor-binding protein 7 (IGFBP7) holding the microvesicular hyperplastic polyp (MVHP) to a small and nonprogressive lesion." (PMID 30034186, 2018).
idiopathic pulmonary fibrosis (2 papers, 2013 to 2023). Idiopathic pulmonary fibrosis (IPF) is a nonneoplastic pulmonary disease that is characterized by the formation of scar tissue within the lungs in the absence of any known cause. "Specifically, previous studies have shown a significant increase in IGFBP7 expression in the lung tissue of patients with fibrotic lungs condition such as Systemic Sclerosis-associated fibrotic lung disease (SSc-FP) and Idiopathic Pulmonary Fibrosis (IPF), but not in those with SSc-PAH." (PMID 37936223, 2023). "However, the role of IGFBP-7, which has a normal serum concentration of 33 ng/ml, in pulmonary fibrosis is unknown." (PMID 23350749, 2013).
invasive breast carcinoma (2 papers, 2008 to 2014). A carcinoma that infiltrates the breast parenchyma. "High grade invasive breast cancers lack IGFBP7 expression, which suggests that IGFBP7 may be associated with tumorigenesis." (PMID 19019211, 2008). "Immunohistochemical analysis revealed that while normal breast tissues show strong IGFBP7 expression, invasive breast cancer tissues do not express IGFBP7." (PMID 19019211, 2008).
invasive carcinoma (2 papers, 2014 to 2023). A carcinoma that is not confined to the epithelium, and has spread to the surrounding stroma. "By immunohistochemistry (IHC), they proved that IGFBP7 expression in blood vessels is upregulated in ductal carcinoma in situ (DCIS) compared with normal tissue, while IGFBP7 expression in cancer-associated fibroblasts (CAFs) is more extensive in invasive carcinomas than in DCIS." (PMID 37660019, 2023).
lung adenocarcinoma (2 papers, 2019 to 2025). A carcinoma that arises from the lung and is characterized by the presence of malignant glandular epithelial cells. "We found that the expression of the IGFBP7 gene in lung adenocarcinoma had a significant positive correlation with the proportions of immune cells, including CD8+ T cells, Tregs, and macrophages (p < 0.05)." (PMID 40224214, 2025). "Molecular manipulations were performed to investigate the roles of insulin-like growth factor binding protein 7 (IGFBP7) in lung adenocarcinoma." (PMID 30609749, 2019). "We collected a cohort (102 lung adenocarcinoma specimens) for IGFBP7 immunohistochemical (IHC) staining." (PMID 30609749, 2019). "Molecular manipulations were conducted to investigate the roles of IGFBP7 in TKI-resistant lung adenocarcinoma." (PMID 30609749, 2019). "Furthermore, IGFBP7 expression is strongly associated with infiltration levels of CD8+ T cells, Tregs, and macrophage cells in lung adenocarcinoma." (PMID 40224214, 2025). "Serum IGFBP7 levels before EGFR-TKI treatment could predict PFS with EGFR-TKI treatment in patients with EGFR-mutant lung adenocarcinoma." (PMID 30609749, 2019). "To confirm the change in IGFBP7 after acquired resistance to EGFR-TKIs, we collected 24 malignant pleural effusions of EGFR-mutant lung adenocarcinoma for IGFBP7 mRNA analysis." (PMID 30609749, 2019).
lung diseases (2 papers, 2015 to 2019). "In addition, patients with non-small cell lung cancer (NSCLC) had higher IGF1 and lower IGFBP-3 and IGFBP-7 serum and tumor tissue concentrations compared to patients with noncancerous lung diseases." (PMID 31565100, 2019).
mantle cell lymphoma (2 papers, 2023 to 2026). Mantle cell lymphoma is a rare form of malignant non-Hodgkin lymphoma affecting B lymphocytes in the lymph nodes in a region called the ``mantle zone''. "For example, mantle cell lymphoma patients with high IGFBP7 expression would embrace a favorable survival (Carreras, Nakamura & Hamoudi, 2022)." (PMID 37304887, 2023).
meningioma (2 papers, 2022 to 2024). A generally slow growing tumor attached to the dura mater. "The gene for insulin-like growth factor-binding protein 7 (IGFBP7) was initially identified and characterized as a gene suppressed in meningiomas." (PMID 39045455, 2024). "We noticed that genes such as TGFBI, SNAI1, MMP2, TGFB1, TGFB2, IGFBP7, and LTBP2 were upregulated by the treatment of M2-MDEs in meningioma cells and may contribute to tumor invasion and proliferation behavior." (PMID 35637794, 2022).
Mesenchymal Tumors (2 papers, 2015 to 2020). "Expression of IGFBP7 was also detected in cancer-associated fibroblasts, endothelial cells, mesenchymal tumours and malignant epithelial cells with a mesenchymal phenotype." (PMID 25887188, 2015). "We will now give an outline of studies of IGFBP7 and their importance in malignant neoplasms, such as epithelial tumors and mesenchymal tumors." (PMID 32500027, 2020).
parasitemia (2 papers, 2020 to 2021). "Interestingly, parasitemia as low as 0.25% was sufficient to significantly stimulate THP-1 to secrete more IGFBP7." (PMID 32066522, 2020). "Further increase in parasite density (up to 16% parasitemia) did not significantly increase IGFBP7 secretion any further." (PMID 32066522, 2020).
renal failure (2 papers, 2015 to 2024). "ROC curve analysis demonstrated that U IGFBP-7/creatinine ratio, U TIMP2/creatinine ratio, and serum transgelin had predictive value for renal insufficiency (eGFR < 60mL/min/1.73 m2)." (PMID 38708150, 2024). "U IGFBP-7/creatinine ratio, U TIMP2/creatinine ratio, and serum transgelin levels were higher in patients with MM than healthy controls, and predicted renal insufficiency in MM." (PMID 38708150, 2024).
renal fibrosis (2 papers, 2018 to 2025). A final common manifestation of a wide variety of chronic kidney diseases characterized by glomerulosclerosis and tubulointerstitial fibrosis. "IGFBP-7 knockdown attenuates renal fibrosis and improves renal function through activation of ERK1/2 signaling." (PMID 41226289, 2025). "Urinary IGFBP-7 (along with TIMP-2) has been reported as a well-validated biomarker for renal fibrosis." (PMID 41226289, 2025). "TGF-β1 have also induced elevation of Smad2 expressions that promoted renal fibrosis via insulin like growth factor binding protein-7 (IGFBP7)." (PMID 30496316, 2018).
respiratory failure (2 papers, 2019 to 2023). The significant impairment of gas exchange within the lungs resulting in hypoxia, hypercarbia, or both, to the extent that organ tissue perfusion is severely compromised. "The initial studies validating [TIMP-2]•[IGFBP7] enrolled patients with cardiovascular or respiratory failure going to the ICU." (PMID 31221200, 2019). "Therefore, [TIMP-2]•[IGFBP7] testing is most often being ordered in patients at risk for AKI, including those who are hemodynamically unstable, in respiratory failure, or exhibiting Stage 1 AKI." (PMID 31221200, 2019).
scleroderma (2 papers, 2023 to 2025). Scleroderma is a rare autoimmune connective tissue disorder characterized by abnormal hardening of the skin and, sometimes, other organs. "IGFBP7hi ECs were increased in SLE (IFN dominant) and scleroderma (IFN related), but not in AD (Th2 dominant), suggesting that IGFBP7hi ECs and IGFBP7-induced endothelial glycocalyx degradation may be more common in Th1-related skin diseases." (PMID 36917196, 2023).
skin cancer (2 papers, 2015 to 2016). "A previous study in skin cancer suggested that decreased RNA editing levels of IGFBP7 results from failure to edit excess amount of highly expressed IGFBP7 transcripts in tumors; however, in our analysis only HNSC showed a significant increase in IGFBP7 total mRNA levels (P-value ≤0.05)." (PMID 26980570, 2016). "IGFBP7 has been proposed as a candidate tumour suppressor gene as suggested by experiments demonstrating suppression of tumourigenicity in murine lung, prostate and colorectal, breast and skin cancers xenograft models with rIGFBP7." (PMID 25886299, 2015).
squamous cell carcinoma (2 papers, 2015 to 2021). A carcinoma arising from squamous epithelial cells. "In the normal epidermis, IGFBP7 transcripts are highly edited, but this editing is significantly reduced in basal cell and squamous cell carcinomas." (PMID 34899345, 2021). "IGFBP7 transcripts are highly edited in the normal epidermis, while this editing is significantly reduced in basal cell and squamous cell carcinomas; 4) A-to-I is regulated by the ADAR enzyme RNA editing, thereby regulating the editing level of oncogenes and regulating the development of cancer." (PMID 34899345, 2021). "Initial proteomic analysis of the secretome of two NSCLC subtypes, A549 (adenocarcinoma) and SK-MES-1 (squamous cell carcinoma), detected several secreted proteins with a potential role in tumour development or metastasis i.e. CC, CL, IGFBP-7, VEGF-A and TNF-α." (PMID 26407999, 2015).
vasculitis (2 papers, 2015 to 2023). "Subsequently, non-significant increases in [TIMP-2]•[IGFBP7] were found for typical HUS (P = 0.51), hypovolemia/dehydration, interstitial nephritis, nephrotoxic AKI, renal vein thrombosis, perinatal asphyxia and vasculitis." (PMID 26606754, 2015).
abdominal aortic aneurysm (1 paper, 2024). Enlargement and ballooning of the vessel that supplies arterial blood to the abdomen, pelvis and legs. "Contrary to these data, an observational study focused on the AKI development in patients who underwent abdominal aortic aneurysm repair showed that urinary concentration of TIMP2*IGFBP7 neither changed significantly at baseline nor post-operatively." (PMID 39596140, 2024).
acute leukemia (1 paper, 2015). A clonal (malignant) hematopoietic disorder with an acute onset, affecting the bone marrow and the peripheral blood. "Here we investigated the functional role of IGFBP7 in acute leukemia and its possible mode of action." (PMID 26450156, 2015). "Several studies have revealed a link between IGFBP7 and acute leukemia: in childhood AML and ALL IGFBP7 was found to be up-regulated and high expression was associated with lower survival in precursor B-cell Ph(−) ALL patients." (PMID 26450156, 2015). "However, further actions and downstream targets of IGFBP7 in acute leukemia remain yet to be investigated." (PMID 26450156, 2015).
acute lung injury (1 paper, 2024). A condition of lung damage that is characterized by bilateral pulmonary infiltrates (pulmonary edema) rich in neutrophils, and in the absence of clinical heart failure. "IGFBP7 has been found to play an important role in inflammatory diseases, such as acute lung injury (ALI)." (PMID 38840498, 2024).
advanced heart failure (1 paper, 2022). Patients with advanced heart failure have severe limitations, experiences symptoms even while at rest and are mostly bedbound patients. "Random forest analysis identified IGFBP7 as the protein most strongly involved in the classification between non-advanced and advanced heart failure." (PMID 35672400, 2022).
anaplastic carcinoma (1 paper, 2019). "Taken together, results from the present study showed that the expression of IGFBP7 is significantly downregulated and even absent in thyroid follicular carcinoma and anaplastic carcinoma tissues." (PMID 31183073, 2019).
anaplastic thyroid carcinoma (1 paper, 2019). "In this study, we found that IGFBP7 expression is greatly decreased and even absent in follicular and anaplastic thyroid carcinoma compared to that in normal thyroid tissue, adenoma and classical PTC." (PMID 31183073, 2019).
anemia (1 paper, 2025). A reduction in the number of red blood cells, the amount of hemoglobin, and/or the volume of packed red blood cells. "Furthermore, both biomarkers showed significant negative correlations with hemoglobin (r = −0.425, p = 0.002 for IGFBP-7; r = −0.463, p = 0.001 for TIMP-2), reflecting their association with anemia." (PMID 40369504, 2025).
aneurysm (1 paper, 2018). Bulging or ballooning in an area of an artery secondary to arterial wall weakening. "Out of which, IGFBP7 seems a very promising site for future research, both for its extremely high editing activity and for its past implication in vascular pathologies such as aneurysm formation and pulmonary stenosis." (PMID 30087110, 2018).
arteriosclerosis of (1 paper, 2022). "All subjects in the control, IHD, and PAD groups had additional cardiovascular risk factors, but only patients with confirmed arteriosclerosis of the lower extremities or coronary arteries had significantly elevated IGFBP-7 levels." (PMID 35625639, 2022).
astrocytomas (1 paper, 2024). "In summary, the IGFBP7 Risk Score (IGRS) provided a robust prognostic tool for astrocytomas by categorizing patients into High and Low IGRS groups, with High IGRS correlating with worse outcomes." (PMID 39403379, 2024).
benign thyroid tumors (1 paper, 2019). "Notably, our current study demonstrated that the expression of IGFBP7 in FTC and ATC is significantly lower or even absent compared with that in normal thyroid tissues, benign thyroid tumors and PTC." (PMID 31183073, 2019).
brain injury (1 paper, 2020). Acute and chronic (see also brain INJURIES, CHRONIC) injuries to the brain, including the cerebral hemispheres, CEREBELLUM, and brain STEM. "In this study, we showed that Igfbp7/IGFBP7 is up-regulated in the vasculature in both TBI mice models and surgical samples from patients with brain injury." (PMID 33505428, 2020).
colon adenoma (1 paper, 2020). An adenoma that arises from the colon. "To confirm activated TGFβ signaling in mouse colon adenomas, we performed immunostaining for the TGFβ signaling component pSMAD3 and the TGFβ‐target gene IGFBP7." (PMID 31793740, 2020).
colonic adenocarcinoma (1 paper, 2010). "In 1999, we separated the insulin-like growth factor binding protein 7 (IGFBP7) cDNA fragments from colonic adenocarcinoma and normal mucosa cDNA subtraction libraries by suppressive subtractive hybridization (SSH)." (PMID 20433702, 2010).
cystic fibrosis-related diabetes (1 paper, 2024). Cystic fibrosis-related diabetes is a form of diabetes that occurs frequently in individuals with cystic fibrosis. "A similar shift with lower IGFBP7 expression in ductal cells, and then an increase in intraparenchymal cells is seen in a cystic fibrosis-related diabetes (CFRD) animal model where IGFBP7 was suggested to mediate pathological intrapancreatic crosstalk." (PMID 39280605, 2024).
dental caries (1 paper, 2023). The decay of a tooth, in which it becomes softened, discolored, and/or porous. "A total of 39 independent vQTLs with p < 1 × 10−6 were identified, some of which were located in or near genes with plausible biological roles in dental caries (IGFBP7, SLC5A8, and SHH involved in tooth development and enamel mineralization)." (PMID 36981009, 2023). "Our results suggest that the effects of IGFBP7 on dental caries, potentially through its role in tooth development and mineralization, may be different between breastfed and non-breastfed children." (PMID 36981009, 2023).
endometrial cancer (1 paper, 2008). Primary or metastatic malignant neoplasm involving the endometrium (mucous membrane that lines the endometrial cavity). "Furthermore, serum IGFBP7 levels in patients with colorectal, esophageal, or endometrial cancer were not different than normal healthy subjects." (PMID 19019211, 2008).
endometrial polyp (1 paper, 2021). A benign nodular lesion protruding above the surface of the endometrium. "To determine whether polypectomy influences the expression of implantation-related factors, we examined the effects of excision on the expression levels of the IGFBP1, IGFBP7, PTGS2, and CALR mRNAs in 27 patients with endometrial polyps." (PMID 34638846, 2021).
gastric diseases (1 paper, 2021). "The results indicate that IGFBP7 may play an important role in the immune regulation of H. pylori-related gastric diseases." (PMID 33531979, 2021).
glaucoma (1 paper, 2024). Increased pressure in the eyeball due to obstruction of the outflow of aqueous humor. "A total of 11 unique protein-coding genes posterior probability (PP) of H4 > 0.70 finally remained, including GSTM3 for senile cataract, WARS1, C3, IGFBP7, and PILRA for AMD, ECI1, LCT, and NPTXR for glaucoma, EFEMP1 for myopia, and SIRPG and SIGLEC14 for DR." (PMID 39408566, 2024).
Hepatitis (1 paper, 2020). Inflammation of the liver. "For instance, the promoter methylation status of two factors, TFPI2 and IGFBP7, in serum is markedly higher than that in normal subjects and hepatitis patients and may thereby become a non-invasive molecular biomarker for the early diagnosis of HCC in the clinic." (PMID 32831081, 2020).